CSF1 (colony stimulating factor 1)
Diseases named in the same sentence as CSF1 in open-access papers (continued):
Sharing a sentence is not in itself a finding about the gene and the disease.
cancer (continued). "Attempts to eliminate TAMs using mAbs against colony stimulating factor 1 (CSF-1) or small molecule inhibitors targeting the c-fms tyrosine kinase of its receptor (CSF-1R/CD115) have proven effective in various murine cancer models and are investigated in numerous clinical trials." (PMID 30938231, 2019). "Moreover, in a co-cultured context with FGFR3-driven cancer cell line and CSF-1-differentiated human macrophages, 3D185 inhibited macrophages induced cancer cell migration with potency much better than AZD4547 and PLX-3397." (PMID 31438996, 2019). "Exposure of macrophages to IL-4, colony-stimulating factor-1 (CSF1), granulocyte-macrophage colony-stimulating factor (GM-CSF), and TGFβ secreted by cancer cells polarize macrophages to the M2 phenotype, which acts to induce immunosuppressive microenvironments." (PMID 30736371, 2019). "In parallel, 3D185 could potently inhibit the proliferation of CSF-1/CSF-1R-dependent cancer cell lines and the survival of CSF-1-induced M2-like ‘protumor’ macrophages." (PMID 31438996, 2019). "In addition, 3D185 inhibited CSF-1-differentiated macrophages induced FGFR3-aberrant cancer cell migration with potency much better than AZD4547 and PLX-3397." (PMID 31438996, 2019). "Furthermore, recent findings indicate that CSF-1 signal transduction pathways have an autocrine-loop function in cancer cells." (PMID 31565097, 2019). "First, the expression of CSF-1 was higher in UTUC tissues than in cancer-adjacent normal tissues." (PMID 31565097, 2019). "Besides, high expression of miRNA-1207-5p or low expression of CSF1 provided a better survival chance for NSCLC patients when compared to cancer with low expression of miRNA-1207-5p or high expression of CSF1." (PMID 30944831, 2019). "However, recent studies placed a cautionary note on blocking CSF-1 signaling as a therapeutic modality in cancer." (PMID 31406165, 2019). "Blocking CSF1, the main factor to recruit and sustain TAMs, by antibodies or inhibitors, has been one of the most effective way to target and decrease TAMs, thus inhibiting cancer progression and metastasis." (PMID 30563983, 2018). "The overexpression of CSF1 has also been found in various cancers in paracrine or autocrine ways." (PMID 28286742, 2017). "Moreover, intracellular CSF-1R signaling not only regulates cancer cell survival and migration, but also stimulates CSF-1/CSF-1R, indicating that the expression of CSF-1 and CSF-1R is influenced by an autocrine loop." (PMID 29228668, 2017). "A variety of small molecules and monoclonal antibodies (mAbs) directed at CSF1R or its ligand CSF1 are in clinical development both as monotherapy and in combination with standard treatment modalities such as chemotherapy as well as other cancer-immunotherapy approaches." (PMID 28716061, 2017). "This review focuses on motility signals transduced by the CSF-1R upon activation by CSF-1, and how these signals might be targeted to treat disease, particularly cancer." (PMID 28629162, 2017). "CSF-1R and CSF-1 are modulated by the autocrine system contributing to aggressive cancers." (PMID 29228668, 2017). "CSF-1 produced by carcinoma cells enhances the expression of EGF by macrophages." (PMID 28567162, 2017). "Moreover, EGF promotes CSF-1 expression by carcinoma cells thereby generating a positive feedback loop." (PMID 28567162, 2017). "Subsequent to the original isolation of human CSF1 cDNA in the 1980s and demonstration that injection of the recombinant CSF1 protein can expand macrophage populations in mice, there were a number of clinical trials of applications in cancer and other indications." (PMID 27445344, 2016). "Besides interfering with survival- and metabolism-related targets in cancer cells, the presence of macrophages also modulated the expression of macrophage-stimulating factor 1 (CSF1), an important molecule for macrophage recruitment." (PMID 27513864, 2016).
cancer (continued). "Our own experiments showed that targeting of CSF-1/CSF-1R axis may be a good therapeutic approach in cancer cells." (PMID 27212807, 2016). "Colony-stimulating factor-1 (CSF-1) has been well documented as a powerful regulator of macrophage proliferation, differentiation, and survival, and high levels of CSF-1 and its receptor were later found to point out to human cancers with poor prognosis." (PMID 27376091, 2016). "CSF-1 is an important mediator of the interaction between macrophages and cancer cells." (PMID 26174804, 2015). "For example, CCR1, IL1RAP, CCL22 and CSF1 are all involved in metastatic dissemination, and their aberrant expression correlates with leukocyte infiltration and aggressive phenotype in various cancer types." (PMID 26536459, 2015). "Elevated expression of CSF-1 and TGF-β1 in the secretome of MDCKYBX1 cells could promote several aspects of carcinogenesis, as these molecules have been heavily implicated in cancer-related processes." (PMID 25980435, 2015). "Furthermore, it was shown that this interaction is mediated by a CSF-1/EGF-loop between carcinoma cells and MCs." (PMID 26098772, 2015). "Colony stimulated factor-1 (CSF-1) could serve as a possible target, known to be part of a paracrine loop between carcinoma cells and blood-derived macrophages (MCs)." (PMID 26098772, 2015). "Taken together, our results suggest that Vav1 may propagate a putative autocrine feed forward loop by upregulating expression of CSF1, which in turn induces Vav1 tyrosine phosphorylation in cancer cells." (PMID 25313137, 2014). "CSF-1 treatment neither caused any significant effect on apoptosis in cancer cells grown in normal medium, nor in cells grown in serum-starved conditions." (PMID 23561040, 2013). "CSF-1 overexpression by bone metastases may also contribute to the differentiation of osteoclasts, leading to bone lesions and pain in cancer patients." (PMID 24019914, 2013). "Malignant cancer cells release CSF-1, which induces macrophages to express the CSF-1 receptor." (PMID 24116086, 2013). "Following BRAF activation, Csf-1 is markedly overexpressed in the murine cancers." (PMID 23372702, 2013). "Thus accumulating evidence indicates a potentially important role of CSF1 signaling in cancer biology, and many anti-CSF1 approaches are currently being developed." (PMID 20981142, 2010). "The CSF1 produced by cancer cells promotes the expression of EGF by macrophages." (PMID 17242701, 2007). "In addition, EGF promotes the expression of CSF-1 by cancer cells, thereby generating a positive feedback loop." (PMID 17242701, 2007). "Cancer cells of growing ribociclib-resistant tumors used a diverse set of M2-like differentiation stimulating communication pathways as shown by a range of markers: CSF1, CLCF1, several FGFs (1/2/7/17/18/23), the TGF family member GDF9, interleukin 5/11/12, MADCAM1 and PLAU." (PMID 40032842, 2025). "Additionally, beyond polarization, cancer cells stimulate TAM amplification by secreting colony-stimulating factor 1 (CSF1, a key regulator that sustains the protumorigenic functions of TAMs), the E3 ligase Cop1, and the metabolite β-glucosylceramide, all of which enhance TAM activity." (PMID 39865337, 2025). "In addition, targeting CSF1 has already been applied in cancer therapy." (PMID 39936998, 2025). "However, considering the fact that the major TSGCT components are mono/macrophage lineages expressing CSF1R, outweighing the small portion of cancer cells with CSF1 autocrine and paracrine, CSF1R inhibitors have been designed to selectively target TSGCT non-neoplastic components to shrink tumors." (PMID 40563544, 2025). "Moreover, Csf1 is elevated in numerous cancers, including reproductive cancers; thus, elevated Csf1 and macrophage dysregulation might similarly contribute to adverse effects on fertility in this context." (PMID 37992158, 2023).
cancer (continued). "CSF1R, the cellular receptor for Colony Stimulating Factor-1 (CSF1) and Interleukin 34 (IL-34), occupies a central role in manipulating the behavior of TAMs, and the dysregulation of CSF1R signaling has been implicated in cancer progression and immunosuppression in many specific cancers." (PMID 36983741, 2023). "CSF-1 appears to play an autocrine and/or paracrine role in cancers of the ovary, endometrium, breast, lung, the nervous system, and myeloid and lymphoid tissues, within which overexpression of CSF-1 receptor is considered as a prognostic factor for survival in cancer." (PMID 35326399, 2022). "Interestingly, cancer cells can produce a series of factors, including IL-4, colony stimulating factor-1 (CSF-1) and platelet-derived growth factor-BB (PDGF-BB), directly or indirectly in a pericyte- and fibroblast-derived IL-33-dependent manner to recruit TAMs, and thus promote metastasis." (PMID 36046433, 2021). "Indeed, the inhibition of either EGF or CSF1 results in strong cancer cell migration diminution." (PMID 33783686, 2021). "Moreover, CSF-1 has also been reported to be aberrantly expressed in several human cancers." (PMID 31565097, 2019). "In addition, 3D185 could inhibit the survival and M2-like polarization of macrophages, reversing the immunosuppressive effect of macrophages on CD8+ T cells as well as CSF1-differentiated macrophage induced-FGFR3-aberrant cancer cell migration." (PMID 31438996, 2019). "The levels of CSF1, the other ligand of CSF1R, remained unchanged in IL34-OE cancer cells, indicating that the increase in MD-TAMs was a direct consequence of an IL34-enriched TME." (PMID 40538439, 2025). "The Anushka team has shown through their studies that the targeting and removal of important elements such as CD73, CSF1, or SPP1 secreted by quiescent metastatic cancer cells can significantly disrupt the establishment of the immunosuppressive TME." (PMID 40303328, 2025). "Targeting colony-stimulating factor 1 (CSF1) and CSF1 receptor (CSF1R) for M2 macrophage reprogramming has been widely implemented in clinical trials for cancer therapy." (PMID 40821781, 2025). "During the metastasis, TAMs and cancer cells develop a symbiotic relationship by releasing the epidermal growth factor (EGF) and colony-stimulating factor 1 (CSF-1), respectively." (PMID 38361941, 2024). "Colony-stimulating factor 1 (CSF1) secreted by PDAC cells can recruit and stimulate macrophages to promote the chemotaxis of cancer cells." (PMID 39119085, 2024). "Macrophages secrete high levels of colony-stimulating factor-1 (CSF-1) in GBM tumors, promoting cancer cell proliferation and survival." (PMID 39200265, 2024). "TAM-membrane-coated nanoparticles can scavenge CSF1, thereby disrupting TAM–cancer cell interactions and enhancing the effectiveness of cancer immunotherapy." (PMID 39120393, 2024). "In response to cancer cell secretion of CCL8, the production of colony-stimulating factor-1 (CSF1), a critical factor supporting macrophage survival and proliferation, is stimulated, thus perpetuating the auto-stimulatory cycle." (PMID 39410029, 2024). "Using secretome and gene expression analysis, we found that BaP-4 cells also significantly downregulated M-CSF protein and Csf1 gene expression levels compared with DMSO-1 control cancer cells." (PMID 37843274, 2023). "The activation of genes such as NR4A3, MET, ZEB1, CSF1, CSF2, CSF3, which can be involved in transcriptional dysregulation in cancer or hematopoietic cell lineage signaling pathways, can also be involved in cell differentiation." (PMID 37606991, 2023). "Cells in the TME regulate cancer growth through mitogenic and growth-inhibitory signals, and cancer cells produce VEGF, platelet-derived growth factor (PDGF), and colony-stimulating factor 1 to mobilize macrophages, resulting in cell–cell interactions." (PMID 36769116, 2023).
cancer (continued). "Cancer cells express various cytokines, chemokines, and growth factors such as IL-6, CCL2, CXCL8, CSF1, and CSF2, which impact vascular permeability, lymph angiogenesis, and metastasis." (PMID 37894465, 2023). "We found that IFNA1 and IFNL1 gene transcripts resulted negligibly expressed across the pan-cancer dataset when compared to other immunosuppressive and pro-inflammatory cytokines such as TGFB1/2, PTGES2, IL1A, IL1B, IL6 and CSF1." (PMID 38239354, 2023). "Highly invasive cancer cells release high quantities of CCL2 and colony-stimulating factor 1 (CSF1) to attract and localize TAMs in metastatic locations." (PMID 37892995, 2023). "CSF-1, in turn, recruits and activates TAMs to further secrete EGF, indicating the presence of an EGF/CSF-1 positive feedback loop between TAMs and cancer cells." (PMID 37445965, 2023). "Also, key subtype differences in immunomodulatory and matrix-modifying protein release identified in our previous experiments could be captured in serum, such as high Loxl1 and Csf1 secretion by mesenchymal cancer cells, providing direct evidence for potential long-range effects." (PMID 37156840, 2023). "In recurrent cancers, combining a PI3K or IGF-1 inhibitor with a CSF-1 inhibitor has dramatically extended the OS and has provided a novel approach for CSF-1 inhibitor resistance." (PMID 36146527, 2022). "Increased expression of CSF1 and CSF1R were found to be specific to cancer regions in high-grade PCa (e.g., Gleason 9) in comparison to normal adjacent regions (n = 3 patients)." (PMID 36209194, 2022). "Together, our data indicate that HB-EGF, shed from cancer cells by ADAM17, amplifies TNF-α and CSF-1 signaling in nearby macrophages." (PMID 35998057, 2022). "In a mouse model, PTC tumors expressing BRAFV600E show high TAM infiltration in response to increased expression of TAM chemoattractant, colony stimulating factor-1 (CSF-1), and chemokine CCL2 by cancer cells." (PMID 36230610, 2022). "Protein enrichment involved with cancer stem cell signaling, EMT, and inflammatory process were identified as cores for cancer invasion and metastatic process related with TWIST1 and CSF1 overexpression." (PMID 33466385, 2021). "Accordingly, breast cancer cells expressing EGFR secrete CSF-1 and attract macrophages, which secrete EGF in the vicinity of cancer cells, thus permitting cancer cell migration." (PMID 34206026, 2021). "It has already been shown, in the same cancer model, that targeting CLC2 and CSF1 impairs TAMs recruitment and M2 polarisation, as we here obtained by targeting FOXE1 as well." (PMID 34299284, 2021). "Colony-stimulating factor 1 (CSF-1), vascular endothelial growth factor A (VEGF-A), and different CCL were found to act as chemotactic molecules in various cancer." (PMID 33418996, 2021). "In the TME, the surface of M1 macrophages is rich in TLR2/TLR4, CD80, CD86, CD40, CSF1, IL-1R1, INF-γ-R and MHC-II receptors, which are often used as targets for cancer therapy." (PMID 34683963, 2021). "The differences in cell differentiation and cancer-related genes (AFP, NOTCH1, CSF1, NOTUM, TGFβ, and vimentin genes) implied different biological characteristics between cells cultured in the 3D and 2D models." (PMID 32582546, 2020). "In a murine model of BRAFV600E-induced PTC, tumors showed a high TAM infiltration due to the increased expression of TAM chemoattractants CSF-1 (colony stimulating factor 1) and C-C motif chemokine ligand (CCL) 2 by cancer cells." (PMID 33986723, 2020). "In many tumors, TAM is recruited into microenvironments by CCL2, CSF-1, IL-10, TGF-β, etc. secreted from cancer cells." (PMID 31963413, 2020). "We also identified an auto-regulatory loop between TAMs and cancer cells driven by tumor necrosis factor alpha involving SIGLEC1 and CCL8, which is self-reinforcing through the production of CSF1." (PMID 30930117, 2019).
cancer (continued). "Nine proteins, including LG3BP, CSF1, and NKG2D, known to play important roles in the proliferation and metastasis of cancer, were changed significantly." (PMID 31090175, 2019). "Interactions between TAMs and ECM proteins can promote metastasis, and in this regard, CSF-1 and FAK serve as important examples of how the interaction between the ECM and the inflammatory milieu leads to cancer progression." (PMID 31439034, 2019). "To validate the CSF-1 expression, we investigated UTUC tissue samples from 35 patients compared to paired cancer-adjacent normal tissues by immunohistochemistry." (PMID 31565097, 2019). "Macrophages secrete high levels of colony stimulating factor-1 (CSF-1) in GBM tumors, supporting cancer cell proliferation and survival." (PMID 34322663, 2019). "Additionally, cancer cells may consume IL-34 in certain subtypes at the same time, since CSF-1/CSF-1R but not IL-34 were strongly associated with stromal- and immune-score in HER2 and basal subtypes." (PMID 29796177, 2018). "First, we compared IL-34,CSF-1, CSF-1R, PTPRZ1, and SDC1 gene expression between human MCF7, SK-BR-3 and MDA-MB-231 cancer cells in comparison to human THP-1 macrophages." (PMID 29796177, 2018). "Paracrine loops of EGF/colony-stimulating factor 1 (CSF-1) and CCL18/granulocyte-macrophage colony-stimulating factor (GM-CSF) between M2 macrophages and cancer cells have been shown to increase carcinoma cell invasion." (PMID 28804688, 2017). "Various small-molecule kinase inhibitors and antibodies directed against CSF1 or CSF1R were combined with chemotherapies, irradiation, anti-angiogenic or cancer immunotherapies using immunocompetent and immunodeficient mouse models." (PMID 28716061, 2017). "We have shown that there is a cycle mediated by the cytokines CSF-1 and CCL2, whereby cancer cells induce macrophage proliferation and phenotypic changes, and macrophages stimulate cancer cell proliferation." (PMID 26174804, 2015). "By inspecting the human exitron list, we found that EIS affects several cancer-related genes: the cancer marker genes BMI1, KRT5, and MUC1 and the genes involved in cell adhesion (CSF1), migration and metastasis (ZEB2 and KLF17)." (PMID 25934563, 2015). "CSF-1 and CCL2 are known modulators of the fate of macrophages, both driving the production of M2 cells and being correlated to poor prognosis in cancer." (PMID 26174804, 2015). "To determine the effect of inhibition of CSF-1 and CCL2 signalling on cancer cells we utilised the small molecule inhibitors of CSF-1R (GW2580) and CCR2 (RS102895)." (PMID 26174804, 2015). "Microarray analysis and functional testing previously revealed that CSF-1, which was excreted by cancer cell, is the major chemoattractant for RAW 264.7 macrophages migration to cancer cell." (PMID 24116086, 2013). "Cancer cells significantly contribute to an immune-suppressive, pro-tumoral environment, particularly through the secretion of cytokines like IL-10, TGF-β, and colony-stimulating factor-1 (CSF-1)." (PMID 40002754, 2025). "Several reports have revealed that TAMs and CSF-1 are correlated with advanced disease or distant metastasis in conventional GC and cancers of other organs; however, no reports have examined the clinical significance of TAMs and CSF-1 in HAS." (PMID 39488822, 2025). "The ITGB2, CSF1, and CXCR2 genes are closely related to cancer." (PMID 39771147, 2024). "PLX3397was approved by the FDA in 2019 for use in the treatment of diffuse type tenosynovial giant cell tumors (dt-TGCT), a rare and often unresectable non-life-threatening cancer of the tendon sheath that is driven by CSF-1 expressing TAMs." (PMID 37114134, 2023).